IL17RD (interleukin 17 receptor D)
Diseases named in the same sentence as IL17RD in open-access papers:
IL17RD is named in the same sentence as 42 diseases in open-access papers, as found by Europe PMC text mining. Sharing a sentence is not in itself a finding about the gene and the disease. The quoted sentences say what the papers report.
psoriasis (5 papers, 2021 to 2025). An autoimmune condition characterized by red, well-delineated plaques with silvery scales that are usually on the extensor surfaces and scalp. "In a different cellular context, loss of Il17rd in keratinocytes was also shown to partially ameliorate imiquimod (IMQ) induced psoriasis by decreasing IL17A induced infiltration of neutrophils and γδ T cells into the epidermal layer of the skin and regulating keratinocyte expression of Il23." (PMID 33436016, 2021). "Moreover, determining whether IL17RD can be used as a biomarker for cancer, psoriasis or other diseases may have diagnostic and therapeutic implications." (PMID 33436016, 2021). "Interleukin 17 receptor D is involved in controlling inflammation upon mediating IL-17A-induced proinflammatory gene expression as observed in keratinocytes and psoriasis-like skin inflammation." (PMID 38098998, 2023). "Several psoriasis-related genes were among the associated genes of hsa_skin_088763, including GATA6, SIK2, IL17RD, EGR3, FAS, LRIG1, and PPARGC1A." (PMID 34068434, 2021). "Nevertheless, our data strongly indicate that cell-autonomous overexpression of il17rd in peridermal keratinocytes (krt4+) can induce psoriasis-like phenotypes by inhibiting cytoneme extensions, which subsequently leads to a reduction in Notch signaling in undifferentiated keratinocytes." (PMID 40767593, 2025). "In the analysis of significantly expressed genes between psoriasis and normal skin, IL17RC was considered as the most significantly overexpressed gene among the IL17 family members, followed by IL17RD, IL17RA, IL17F, and IL17RE." (PMID 36009523, 2022). "We found that transcription levels of IL17A, IL17C, and IL17F were increased in psoriasis compared with normal skin, which was in parallel with their receptors IL17RA, IL17RC, IL17RD, and IL17RE." (PMID 36009523, 2022).
breast carcinoma (4 papers, 2021 to 2022). "Mechanistically, IL17RD regulates epithelial to mesenchymal transition (EMT) in breast cancer cell lines, and loss of its function promotes EMT and cancer metastasis." (PMID 35761256, 2022). "IL-17RD mRNA is downregulated in breast cancer, which is significantly correlated with tumor progression." (PMID 35846145, 2022). "Importantly, overexpression of IL-17RD was found to inhibit tumor growth in mouse xenograft models of prostate, intestinal and breast cancer." (PMID 33833999, 2021). "IL-17RD expression also restrains the motility and invasion of prostate and breast cancer cells." (PMID 33833999, 2021). "The phenomenon of IL17RD regulation of EMT marker expression was consistently observed in normal breast epithelial cells stimulated with a combination of proinflammatory cytokines as well as in highly metastatic breast cancer cell lines." (PMID 33436016, 2021). "IL17RD was also shown to interact with the elements of the canonical Wingless and Int (WNT) pathway, specifically β-catenin (CTNNB1) to modulate the metastatic and tumorigenic phenotype of breast cancer cells in vitro and in vivo." (PMID 33436016, 2021). "However, of course, IL17RD is not the sole target of TQ, as many other pathways are targeted by TQ in breast cancer or other cancer types, including TNBC." (PMID 35761256, 2022).
colon cancer (4 papers, 2018 to 2022). "The number of identified hub genes has been previously reported to participate in colorectal cancer pathogenesis, downregulation of miR-193a-3p results in upregulation of IL17RD, which promotes colon cancer through inflammation." (PMID 35194111, 2022). "Importantly, we found that genetic inactivation of Il17rd markedly exacerbates the inflammatory response in a model of colitis-associated cancer, illustrated by a strong enrichment in inflammation-related gene signatures in colon tumors and elevated expression of pro-inflammatory cytokines." (PMID 33833999, 2021). "Surprisingly, we did not observe any difference in the number of phospho-ERK1/2 and Ki-67 positive cells between wild type and Il17rd-/- colon tumors in the AOM-DSS model." (PMID 33833999, 2021). "Colon tumors from Il17rd-/- mice showed elevated expression of pro-inflammatory cytokines including IL-17A and IL-6." (PMID 33833999, 2021). "(B) Western blot showing increase of IL-17RD expression in miR-34a-/- colonic tumors." (PMID 30543324, 2018).
prostate carcinoma (4 papers, 2009 to 2021). A carcinoma that arises from epithelial cells of the prostate gland. "IL-17RD also decreased metastatic incidence of xenografted PC3M prostate cancer cells, consistent with clinical observations." (PMID 33833999, 2021). "In a follow-up study on a larger clinical cohort of prostate cancers, the authors reported that IL-17RD is strongly expressed in 74% (32/43 cases) of benign tissues, but in only 21% (37/176 cases) of cancer biopsies." (PMID 33833999, 2021).
colitis (3 papers, 2021 to 2024). Inflammation of the colon. "IL-17RD/Sef, as a regulatory factor for T cell subsets, promotes colitis-associated tumorigenesis and is negatively correlated with survival rates in mice and colorectal cancer patients." (PMID 39906741, 2024). "IL-17RD, which is a predicted target of miR-193a-3p, was found to be up-regulated in colitis-associated cancer tissue as compared to normal controls." (PMID 33833999, 2021). "We further showed that loss of IL-17RD promotes the development of intestinal tumors in the azoxymethane-dextran sodium sulfate (AOM-DSS) model of colitis-associated colorectal cancer." (PMID 33833999, 2021). "Moreover, downregulation of miR-193a-3p in IBD is related with the promotion of colitis-associated colorectal cancer acting on the target mRNAs of the Interleukin-17 receptor D (IL-17RD) and the plasminogen activator urokinase (PLAU)." (PMID 39203856, 2024). "In the AOM-DSS model, we observed that Il17rd-/- mice display an exacerbated inflammatory response characterized by a higher colitis score, increased immune cell infiltration in colonic tissue, and an increase in circulating pro-inflammatory cytokines." (PMID 33833999, 2021).
colorectal cancer (3 papers, 2021 to 2024). A primary or metastatic malignant neoplasm that affects the colon or rectum. "IL17RD is significantly downregulated in the microsatellite instability subgroup of colorectal cancer patients." (PMID 33833999, 2021). "Depletion of NEAT1 by shRNA in LOVO and HCT 116 colorectal cancer cell lines downregulated IL-17RD mRNA expression, and decreased the tumor growth rate of LOVO xenografts." (PMID 33833999, 2021).
Arthritis (2 papers, 2017 to 2021). Inflammation of a joint. "IL-17RD expression in synovial tissues from SKG mice with mild arthritis (arthritis score: 0.5) was higher than that from SKG mice with severe arthritis (arthritis score: 2.5)." (PMID 28056105, 2017). "In order to examine the correlation between IL-17RD expression and the severity of arthritis, we analyzed immunohistochemical staining of IL-17RD in synovial tissues from ß-glucan injected SKG mice and human RA patients." (PMID 28056105, 2017). "In addition, IL-17RD expression in synovial tissues with mild arthritis (stage 2 RA patient) was higher than that with severe arthritis (stage 4 RA patient), indicating the inverse correlation between IL-17RD expression and the severity of arthritis." (PMID 28056105, 2017). "IL-17RD expression in synovial tissues from SKG mice and RA patients was inversely correlated with the severity of arthritis." (PMID 28056105, 2017).
glioma (2 papers, 2020 to 2021). A benign or malignant brain and spinal cord tumor that arises from glial cells (astrocytes, oligodendrocytes, ependymal cells). "Additionally, introduction of circPITX1 could up-regulate IL17RD abundance via reducing the expression of miR-518a-5p and worsen glioma." (PMID 32190004, 2020). "Moreover, circCPA4, circPITX1, circPRKCI, circ_001350 and circHECTD1 are significantly upregulated in glioma and accelerate glioma cell aggressiveness via the let7/CPA4, miR-518a-5p/IL17RD, miR-545, miR-1236 and miR-296-3p axes." (PMID 34745938, 2021).
hearing loss (2 papers, 2021 to 2024). "To date, IL17RD variants have only been reported in patients with KS and nIHH, often exhibiting non-reproductive symptoms such as hearing loss." (PMID 38628584, 2024). "for instance, in the case of patient #18, who had nIHH without hearing loss, two variants were identified in the IL17RD." (PMID 38628584, 2024).
asthma (1 paper, 2022). "IL17RD is in the IL-17 signaling pathway, which is implicated in asthma, and in COPD pathogenesis, potentially by mediating effects of cigarette smoke." (PMID 35104449, 2022). "These signals suggest a spectrum of shared genetic influences, some predominantly influencing asthma (FAM105A, GLB1, PHB, TSLP), others predominantly influencing fixed airflow obstruction (IL17RD, C5orf56, HLA-DQB1)." (PMID 35104449, 2022).
Autoimmunity (1 paper, 2017). The occurrence of an immune reaction against the organism's own cells or tissues. "Among them, we selected Il17rd because IL-17 signaling is well-known to be linked to the pathogenesis of inflammatory diseases and autoimmunity." (PMID 28056105, 2017).
COVID-19 (1 paper, 2022). A disease caused by infection with severe acute respiratory syndrome coronavirus 2. "We speculate that IL17RD, CD74, and TNFSF15 may serve as disease biomarkers in COVID-19." (PMID 36483456, 2022). "Thus, we speculate that IL-17RD, CD74, and TNFSF15 might serve as disease biomarkers for COVID-19." (PMID 36483456, 2022).
hypogonadotropic hypogonadism (1 paper, 2023). Abnormal ovarian or testicular function due to insufficient hormonal stimulation from the hypothalamic-pituitary axis. "Although we identified rare or novel missense variants in several hypogonadotropic hypogonadism genes (e.g. FGF17, HS6ST1, KISS1R, CHD7, IL17RD) definitively linking them to the PSIS phenotype is premature." (PMID 38096238, 2023).
lung carcinoma (1 paper, 2021). "Intriguingly, a recent study reported that shRNA-mediated depletion of IL-17RD in the mouse epithelial-like lung carcinoma cell line 393P, which modestly slows down proliferation, markedly reduces in vivo tumor growth and sensitizes tumors to a MEK1/2 inhibitor." (PMID 33833999, 2021). "Contrary to these studies, other groups reported that IL-17RD overexpression potentiates epidermal growth factor (EGF)-stimulated ERK1/2 activation in 293 cells and steady-state ERK1/2 phosphorylation in mesenchymal lung cancer cells." (PMID 33833999, 2021).
malaria (1 paper, 2013). Malaria is a serious and sometimes fatal disease caused by a parasite that commonly infects a certain type of mosquito which feeds on humans. "Our data demonstrate the first evidence that polymorphisms in IL17 may be associated with uncomplicated malaria in the Cameroonian population while SNPs in, IL10, IL17RD, IRF1, TLR1and TLR9 may be linked with severe malaria in general." (PMID 24312262, 2013). "Our data demonstrate the first evidence that polymorphisms inIL17 may be associated with uncomplicated malaria in the Cameroonian population while SNPs in, IL10 IL17RD, IRF1, TLR1 and TLR9 may be linked with severe malaria." (PMID 24312262, 2013).
medullary thyroid carcinoma (1 paper, 2021). "Furthermore, mutations in IL17RD have also been associated with certain non-epithelial cancers, such as medullary thyroid carcinoma (MTC) and follicular dendritic cell sarcoma (FDCS), in combination with perturbations in other RTK family members." (PMID 33436016, 2021).
pubertal delay (1 paper, 2025). "A family history of pubertal delay was identified in 2 patients with VUS variants in PROK2 and IL17RD." (PMID 40508017, 2025).
type 1 diabetes (1 paper, 2016). "Although no mechanism has yet been proposed to directly connect ITIH1 with beta-cell-related functions, interleukin 17 receptor D is a candidate gene for type 1 diabetes and is overexpressed in response to proinflammatory cytokines." (PMID 27031336, 2016).
uterine cancer (1 paper, 2025). Primary or metastatic malignant neoplasm involving the uterine corpus and/or the cervix.
cancer (13 papers, 2009 to 2025). A tumor composed of atypical neoplastic, often pleomorphic cells that invade other tissues. "There is also growing evidence that IL-17RD is involved in tumorigenesis, as the downregulation of IL-17RD has been observed in various human cancers, and the loss of IL-17RD promotes tumor formation in mice." (PMID 37686343, 2023). "Expression of IL-17RD is down-regulated in various human cancers and recent work has shown that loss of IL-17RD promotes tumor formation in mice." (PMID 33833999, 2021). "We further determined the expression of IL-17 receptor D (IL-17RD), which is downregulated in a high angiogenic niche such as cancer." (PMID 35163148, 2022). "Although the role of IL17 and IL17Rs in cancer are a bit controversial, as some studies reported their role in cancer progression, and indicated IL17RD as a target for cancer therapeutics." (PMID 35761256, 2022). "On the other hand, two contradictory studies suggested that IL-17RD expression promotes cancer cell proliferation." (PMID 33833999, 2021). "Here, we provide an overview of the signaling functions of IL-17RD and review the evidence for its involvement in cancer." (PMID 33833999, 2021). "There are many possible explanations for these discrepancies about the role of IL-17RD in cancer cell proliferation." (PMID 33833999, 2021). "The down-regulation of IL-17RD, an inhibitor of receptor tyrosine kinase signalling has been shown to be common to a variety of human carcinomas." (PMID 24312262, 2013). "IL-17RD restrains the motility and invasion of cancer cells and functions as a tumor suppressor." (PMID 35846145, 2022). "IL17RD is a transmembrane protein, which has a tumor suppressor role, and thus upregulating IL17RD by TQ may open a new door in cancer immunotherapeutic research and TQ based drug development." (PMID 35761256, 2022). "Interestingly, we also observed that expression of pro-inflammatory cytokine genes is up-regulated in the intestinal tissue of aging Il17rd-/- mice, which are prone to various cancers." (PMID 33833999, 2021). "Notably, IL-17RD was found to be the target of several non-coding RNAs in cancer cells." (PMID 33833999, 2021). "IL-17RD is a multifunctional regulator of immune receptors and inflammatory signaling pathways, whereas PLAU is involved in cancer cell migration and angiogenesis." (PMID 39203856, 2024). "Given the multiple in vitro studies documenting the antagonistic effect of IL-17RD on mitogenic signaling pathways and cell proliferation, it is tempting to speculate that the protein may exert its tumor suppressor function by curtailing cancer cell proliferation." (PMID 33833999, 2021). "In vitro studies have shown that IL-17RD exerts inhibitory effects on RTK-induced ERK1/2 MAPK signaling, and possibly other downstream signaling pathways, to restrain the proliferation of various cancer cell lines." (PMID 33833999, 2021). "Moreover, in vitro studies have shown that IL17RD, another ARL11-related protein (score = 0.7), exerts inhibitory effects on MAPK signaling to restrain the proliferation of various cancer cell lines." (PMID 34502169, 2021).
tumor (13 papers, 2009 to 2024). "More recent findings have now provided compelling evidence for a tumor suppressor function of IL-17RD and started to shed light on the underlying biology." (PMID 33833999, 2021). "IL-17RD loss was significantly correlated with tumor progression." (PMID 33833999, 2021). "However, the exact mechanisms underlying the tumor suppressor function of IL-17RD remain unclear and some studies have proposed that IL-17RD may exert pro-tumorigenic effects in certain contexts." (PMID 33833999, 2021). "Research has confirmed that IL-17RD acts as a tumor suppressor factor in mice, primarily by limiting the duration and severity of inflammation." (PMID 39906741, 2024). "Although our recent work has provided compelling evidence for a tumor suppressor function of IL-17RD in mice, other studies have rather suggested that IL-7RD can exert pro-tumorigenic actions in certain contexts." (PMID 33833999, 2021). "Then, we discuss the role of IL-17RD in tumor development and progression, and highlight some of the remaining questions and discrepancies in the field." (PMID 33833999, 2021). "Western blot confirmed that the IL-17RD protein level was upregulated in the miR-34a-/- colon epithelial cells and tumor." (PMID 30543324, 2018). "Another, according to the Context++ score percentile (score > 70) in the TargetScanHuman, we selected the tumor suppressor USP49 with high Context++ score for the subsequent analysis when compared with IL17RD (score = 58), FOSB (score = 88) and SHROOM4 (score = 21)." (PMID 34075026, 2021). "All these findings point toward a possible tumor suppressor role of IL-17RD." (PMID 33833999, 2021). "In addition to KRAS, miR-193a-3p acts on multiple signaling pathways and plays a tumor-suppressive role by regulating the expression of interleukin 17 receptor D (IL17RD) and erb-b2 receptor tyrosine kinase 4 (ERBB4) in CRC." (PMID 35111681, 2021). "Sef (IL-17RD) is a tumor suppressor that is highly conserved in vertebrates." (PMID 29118380, 2017). "Thus, downregulation of IL-17RD expression may favor the creation of an inflammatory tumor microenvironment conducive to tumor development." (PMID 33833999, 2021). "IL-17RD may suppress tumor development and progression by multiple mechanisms." (PMID 33833999, 2021). "However, until recently, the role of IL-17RD in tumor biology had not been studied in vivo." (PMID 33833999, 2021).
infection (4 papers, 2022 to 2024). The state of being infected such as from the introduction of a foreign agent such as serum, vaccine, antigenic substance or organism. "In sea bass brain, il17ra and il17re-like were significantly decreased at 1dpi, whereas il17rb levels were increased at all the infection times, and il17ra and il17rd did at 15 and 1 dpi, respectively." (PMID 38827125, 2024). "In gilthead seabream, the expression profile in the HK was unaffected but, in the brain, il17rb, il17rd, and il17re-like were up-regulated, whereas il17rc was down-regulated to a significant extent at 1-day post-infection (dpi)." (PMID 38827125, 2024). "However, the HK expression of il17rd at 1 and 15 dpi was completely blocked, whereas that of il17re was significantly reduced at all the infection times." (PMID 38827125, 2024). "However, we observed that Th17-related genes (IL-17F, IL-17RD, IL-23, and IL23R) were significantly downregulated, which is similar to previous findings on F. hepatica-induced infection in ovine peripheral blood mononuclear cells." (PMID 35320269, 2022).
IL17RD also shares sentences with these, for which no sentence is quoted: cervical carcinoma (4 papers); Anosmia (1); bone metastasis (1); breast tumor (1); Crohn disease (1); deafness (1); endometrial cancer (1); glioblastoma (1); Meckel -Gruber Syndrome (1); melanoma (1); myopathy (1); nematode infection (1); Noonan syndrome (1); ovarian carcinoma (1); periodontitis (1); pharyngeal cancers (1); prostate (1); prostate tumour (1); squamous cell carcinoma (1); triple-negative breast carcinoma (1).